UNC5C (unc-5 netrin receptor C)
Description:
Receptor for netrin required for axon guidance (By similarity). Mediates axon repulsion of neuronal growth cones in the developing nervous system upon ligand binding (By similarity). NTN1/Netrin-1 binding might cause dissociation of UNC5C from polymerized TUBB3 in microtubules and thereby lead to increased microtubule dynamics and axon repulsion. Might also collaborate with DSCAM in NTN1-mediated axon repulsion independently of DCC (By similarity). Also involved in corticospinal tract axon guidance independently of DCC (By similarity). Involved in dorsal root ganglion axon projection towards the spinal cord. It also acts as a dependence receptor required for apoptosis induction when not associated with netrin ligand (By similarity).
Synonyms: UNC5H3
Tractability: Antibody: UniProt places it where antibodies can reach, with high confidence; its Gene Ontology location is reachable by antibodies, with high confidence; UniProt predicts a signal peptide or a membrane-spanning region. PROTAC: its protein half-life has been measured.
Gene: Protein-coding gene on chromosome 4 (95,162,504 to 95,549,206, reverse strand). Ensembl gene ENSG00000182168.
Subcellular location: Cell membrane; Cell surface; Synapse, synaptosome; Cell projection, axon; Cell projection, dendrite; Cell projection, growth cone; Cell projection, lamellipodium; Cell projection, filopodium
Pathways (Reactome):
Developmental Biology: Netrin mediated repulsion signals
Gene Ontology:
Molecular function: protein binding; protein kinase binding; tubulin binding; netrin receptor activity; netrin receptor activity involved in chemorepulsion
Biological process: dorsal root ganglion development; axon guidance; brain development; chemorepulsion of axon; netrin-activated signaling pathway; signal transduction
Cellular component: cell surface; plasma membrane; filopodium; growth cone; lamellipodium; axon; dendrite; membrane; neuronal cell body; synapse
Genetic constraint (gnomAD): Loss-of-function variants: 44 observed, 87.64 expected, observed/expected ratio (o/e) 0.5, 90% interval 0.39 to 0.65. The upper end of that interval is the gene's LOEUF score, 0.65, which puts it in group 2 of 6, group 1 being the genes least tolerant of losing a copy. Missense variants: 948 observed, 1,099.6 expected, observed/expected ratio (o/e) 0.86, 90% interval 0.82 to 0.91. Synonymous variants: 444 observed, 433.51 expected, observed/expected ratio (o/e) 1.02, 90% interval 0.95 to 1.11.
Homologues: Orthologues: chimpanzee UNC5C (100% identical), macaque UNC5C (99% identical), rabbit UNC5C (98% identical), pig UNC5C (97% identical), dog UNC5C (97% identical), mouse Unc5c (97% identical), rat Unc5c (97% identical), guinea pig UNC5C (96% identical), tropical clawed frog unc5c (86% identical), zebrafish unc5ca (61% identical), zebrafish unc5cb (51% identical), Drosophila melanogaster unc-5 (32% identical), and 1 more. Paralogues in human: UNC5B (63% identical), UNC5D (50% identical), UNC5A (49% identical), UNC5CL (14% identical).
Diseases named in the same sentence as UNC5C in open-access papers:
UNC5C is named in the same sentence as 50 diseases in open-access papers, as found by Europe PMC text mining. Sharing a sentence is not in itself a finding about the gene and the disease. The quoted sentences say what the papers report.
Alzheimer disease (12 papers, 2018 to 2025). A progressive, neurodegenerative disease characterized by loss of function and death of nerve cells in several areas of the brain leading to loss of cognitive function such as memory and language. "Engagement by netrin ligand is thought to suppress the intrinsic apoptotic potential of the UNC5 death domain, while γ-secretase-mediated cleavage of UNC5C has been linked to neuronal apoptosis in Alzheimer’s disease (AD)." (PMID 37039476, 2023). "At present, studies have indicated that UNC5C was associated with colorectal cancer and Alzheimer’s Disease." (PMID 32477968, 2020). "In addition, a rare mutation, T835M, of UNC5C was identified from parametric linkage analysis of late-onset Alzheimer’s disease." (PMID 33520982, 2020). "Moreover, several studies revealed that single nucleotide polymorphism of UNC5C is relevant to Alzheimer’s disease." (PMID 33520982, 2020). "Furthermore, significant expression changes in UNC5A were found in the posterior cingulate brain region of AD patients, while mutations in UNC5C seemed to predispose to late-onset Alzheimer’s disease." (PMID 30213274, 2018). "Finally, although pro‐apoptotic mechanisms downstream from UNC5C remain less characterized, UNC5C intracellular cleavage by γ‐secretase upon Netrin‐1 deficiency has been observed in Alzheimer disease and may also occur in other models." (PMID 34542930, 2021). "The level of Unc5c was decreased in the dorsolateral prefrontal cortices of patients with Alzheimer’s disease-related cerebral amyloid angiopathy." (PMID 33520982, 2020). "For example, we found Alzheimer’s Disease risk genes APOE, PLD3, TREM2, UNC5C, AKAP9, and ADAM10 in our orthologous gene list." (PMID 30382841, 2018). "UNC5C has been previously identified as a candidate gene for Alzheimer’s disease." (PMID 38540364, 2024). "UNC5C has been proposed as a candidate gene for Alzheimer’s disease (AD) in previous studies." (PMID 38540364, 2024). "In initial round of PPI search, I found UNC5C (netrin receptor) interaction with TUBB3 as strong PPI interactions, which is a non-tubulin family of protein involved in neuronal development and also associated with Alzheimer’s disease." (PMID 37466845, 2023). "Findings from ENC1, UNC5C, and TMEM106B converged to suggest a possible role in determining cognitive resilience in the aging population affected by Alzheimer's disease, stroke and other NDs." (PMID 39351424, 2024). "For example ENC1, UNC5C, and TMEM106B have been suggested as determinants of cognitive resilience in the aging population affected by Alzheimer's disease, stroke and other neuropathologies." (PMID 39351424, 2024).
colorectal cancer (9 papers, 2015 to 2025). A primary or metastatic malignant neoplasm that affects the colon or rectum. "Although loss of expression of UNC5C due to epigenetic alterations has been observed in human colorectal cancer, its clinical significance in CRC diagnosis or prognosis remains to be evaluated." (PMID 34922605, 2021). "Intriguingly, the expression of UNC5H receptors was downregulated in colorectal cancer, and UNC5C loss-of-function was associated with intestinal tumor progression in mice." (PMID 32902412, 2020). "Germline mutations in UNC5C have been suggested to increase colorectal cancer (CRC) risk, thus causing hereditary CRC." (PMID 26852919, 2016). "Besides its crucial role in various carcinomas, specifically in Colorectal cancer, UNC5C has also been implicated in various neurological disorders such as Autism spectrum disorder, Schizophrenia, and Parkinson’s disease." (PMID 40468412, 2025). "UNC5C acts as a chemorepellent for Netrin1, while its antagonist, deleted in colorectal cancer (Dcc), acts as a chemoattractant during axon guidance." (PMID 40468412, 2025). "Previous reports have suggested that UNC5C has tumor suppressive effect in colorectal cancer through promoter methylation." (PMID 32477968, 2020). "However, apart from UNC5C, few studies have focused on methylation-mediated inhibition of UNC5 receptors and the associated clinical significance in human colorectal cancer." (PMID 34922605, 2021). "Indeed, we previously reported that UNC5C was silenced by dense methylation of its promoter CpG islands in colorectal cancer." (PMID 26207151, 2015). "Our scRNA-seq data revealed prominent expression of deleted in colorectal cancer (DCC) and DSCAM, and weaker expression of Unc5c, Unc5D, and Neogenin." (PMID 39569362, 2024). "As is the case in colorectal cancer, our results demonstrated that 11/12 gastric cancer cell lines lacking UNC5C expression showed dense methylation in the UNC5C promoter." (PMID 26207151, 2015).
intestinal tumor (5 papers, 2016 to 2021). "For example, in mice, inactivation of UNC5C is associated with increased intestinal tumor progression and decreased tumor cell apoptosis." (PMID 33126652, 2020). "UNC5C, a member of the family UNC5 of netrin receptors, was proposed as candidate gene for CRC predisposition based on previous evidence demonstrating the role of UNC5C and other Netrin I receptors as tumor suppressors and their association with intestinal tumor initiation and progression." (PMID 32585810, 2020).
colon cancer (4 papers, 2011 to 2020). "UNC5C, which encodes ntetrin-1receptor, has been reported to function as tumor suppressor gene in human colon cancer." (PMID 27203079, 2016). "One gene directly targeted by Rhox5 is Unc5c, a tumor suppressor frequently silenced by DNA methylation in colon cancer." (PMID 21609483, 2011). "To evaluate the role of O-GlcNAcylation in the epigenetic downregulation of the UNC5 family, we first examined the expression of UNC5A, UNC5B, UNC5C and UNC5D transcripts in the human colon cancer cell line HCT116." (PMID 33126652, 2020). "In CT26 colon cancer cells, Unc5c is not expressed, and Rhox5 knockdown by shRNA did not change Unc5c expression (data not shown)." (PMID 21609483, 2011). "Consistent with previous reports showing that UNC5C is not expressed in colon cancer cell lines and patient samples due to promoter methylation, transfection of miR-29b-2-5p mimic in HCT-8 colon cancer cells did not affect Shigella binding to host cells." (PMID 28394930, 2017).
Parkinson disease (4 papers, 2007 to 2025). A progressive degenerative disorder of the central nervous system characterized by loss of dopamine producing neurons in the substantia nigra and the presence of Lewy bodies in the substantia nigra and locus coeruleus. "Consistent with this notion, UNC5B has been linked to neurodegeneration in the 6-OHDA model of Parkinson’s disease and UNC5C has been nominated as a risk allele in late-onset AD." (PMID 37039476, 2023). "Together, our findings suggest that UNC5C T835M may promote oxidative stress, which in the presence of a cytotoxic stressor, such as pathologic Aβ or tau (AD) or α-synuclein (Parkinson’s disease), may cause disease pathogenesis." (PMID 40468412, 2025). "Overall, we report an age-associated loss of hippocampal volume and increased hippocampal neuronal loss with age in UNC5C T835M targeted replacement mice, which could serve as a model to study other neurodegenerative diseases such as Parkinson’s and Huntington’s disease." (PMID 40468412, 2025). "In Parkinson’s disease, UNC5C is cleaved by the protease Asparagine Endopeptidase (AEP), contributing to dopaminergic neuronal loss." (PMID 40806170, 2025). "AEP-truncated UNC5C fragmentation promotes neurotoxicity and the aggregation of alpha-synuclein, observed in brains of mouse models for Parkinson’s disease." (PMID 40806170, 2025). "UNC5C maps to the alpha-synuclein locus of chromosome 4, where the SCNA gene is an already well-known Parkinson's disease susceptibility gene." (PMID 17332845, 2007).
breast carcinoma (3 papers, 2020 to 2024). "Consistently, UNC5C inhibits breast cancer metastasis by downregulating MMP9 expression through PI3K/AKT, ERK and p38 MAPK signalling pathways." (PMID 38546656, 2024). "In addition, UNC5C also interacts with integrin α6β4 to prevent breast cancer cell proliferation and metastasis." (PMID 38546656, 2024).
cognitive disorder (2 papers, 2016 to 2023). A disease affects cognitive processes. "UNC5C, a transmembrane receptor of NT-1, plays a role in cognitive impairment during neurodegenerative disease." (PMID 27746720, 2016).
depression (2 papers, 2017 to 2024). "In secondary analyses, we explored the mechanism of these associations and found that ENC1 may be related to the previously documented effect of depression on cognitive decline, while UNC5C may alter the composition of presynaptic terminals." (PMID 28441426, 2017). "For example, among the candidate genes were known susceptibility loci for diabetes (PTPN22, CEP68, RREB1, TCF7L2), coronary artery disease (PSRC1, UNC5C, LPLA), depression (MAD1L1, YLPM1) and insomnia (NMT1)." (PMID 38541061, 2024).
gastric cancer (2 papers, 2015). A primary or metastatic malignant neoplasm involving the stomach. "Next, we examined associations between UNC5C promoter methylation status and the clinicopathological and genetic features of gastric cancers." (PMID 26207151, 2015). "Similar to the DCC alterations in gastric cancer, our data highlight that UNC5C alterations caused by both epigenetic and genetic events were significantly associated with CIN-positive gastric cancers." (PMID 26207151, 2015). "Using this cutoff value, 31/98 gastric cancers (32 %) and 5/105 normal gastric mucosa specimens (5 %) were diagnosed as UNC5C-methylated." (PMID 26207151, 2015). "We found that 39/98 gastric cancers (40 %) and 16/105 normal gastric mucosa specimens (15 %) displayed more than 1 % methylation in the UNC5C promoter." (PMID 26207151, 2015). "Before examining UNC5C expression and methylation status in the UNC5C promoter region in the gastric cancer cell lines, we assessed the expression status of five splicing variants of UCNC5C mRNA (UNC5C-001, 002, 003, 004, and 201) by RT-PCR." (PMID 26207151, 2015). "In the present study, a series of genetic and epigenetic analyses for DCC and UNC5C were performed in a Japanese cohort of 98 sporadic gastric cancers and corresponding normal gastric mucosa specimens." (PMID 26207151, 2015). "In particular, a twofold downregulation of UNC5C expression compared with the corresponding normal tissues was observed in approximately 70 % of gastric cancer cases." (PMID 26207151, 2015). "In clinical specimens, 31/98 gastric cancers (32 %) and 5/105 normal gastric mucosa specimens (5 %) exhibited UNC5C methylation." (PMID 26207151, 2015). "UNC5C methylation status was examined in a cohort of 98 gastric cancers and 105 normal gastric mucosa specimens." (PMID 26207151, 2015). "Both DCC and UNC5C were inactivated in 97 % of CIN-positive gastric cancers and in 55 % of CIN-negative gastric cancers, and these alterations occurred through genetic and epigenetic processes." (PMID 26207151, 2015). "Similar to DCC receptors, other netrin-1 receptors, including UNC5A, UNC5B, and UNC5C, were also discovered as putative tumor suppressor genes in various tumors, including gastric cancer." (PMID 26207151, 2015). "Both DCC and UNC5C were inactivated in 97 % of CIN-positive gastric cancers and in 55 % of CIN-negative gastric cancers." (PMID 26207151, 2015). "More than 5 % methylation in the DCC and UNC5C promoters were found in 45 % (44/98) and 32 % (31/98) gastric cancers, respectively, and in 9 % (9/105) and 5 % (5/105) normal gastric mucosa, respectively." (PMID 26207151, 2015). "Among them, a twofold downregulation of UNC5C expression compared with corresponding normal tissue was observed in approximately 70 % of gastric cancer cases." (PMID 26207151, 2015). "Therefore, we looked for associations between UNC5C and/or DCC defects and TNM stage in the 98 gastric cancers that were informative for both UNC5C and DCC genetic/epigenetic results." (PMID 26207151, 2015). "Our finding that dysregulation of DCC predominantly occurs in the early phase of gastric cancer whereas UNC5C alterations occur later suggests that inactivation of these receptors is not a random process but occurs in a statistically predictable, sequential manner." (PMID 26207151, 2015). "In this study, we hypothesized that downregulation of DCC and UNC5C plays an important growth regulatory function in gastric tumorigenesis, which we addressed by investigating a panel of gastric cancer cell lines and clinical specimens from patients with gastric cancer." (PMID 26207151, 2015). "Among the 10 gastric cancer cell lines, only the GCIY cell line exhibited increased UNC5C mRNA expression levels (lowerΔCT)." (PMID 26207151, 2015). "We found that the frequency of gastric cancers with concurrent alterations in the DCC and UNC5C genes increased in a stage-dependent manner." (PMID 26207151, 2015).
gastric cancer (continued). "Overall, 70 % (58 of 83 informative cases) and 51 % (40 of 79 informative cases) of gastric cancers harbored either LOH or aberrant methylation in the DCC and UNC5C genes, respectively." (PMID 26207151, 2015). "This study investigated the molecular events responsible for the abrogation of the netrin pathway in gastric cancer and the role played by the two dependence receptors, DCC and UNC5C." (PMID 26207151, 2015). "Of 98 gastric cancers, 19 cancers were categorized as non-informative, 39 cancers were categorized as negative for UNC5C alterations, and 40 cancers as positive for UNC5C alterations." (PMID 26207151, 2015). "MSI-positive gastric cancers were significantly more frequent in gastric cancers with UNC5C methylation compared with those without UNC5C methylation (26 vs. 7 %, P = 0.013)." (PMID 26207151, 2015). "Because UNC5C and DCC both serve as dependence receptors for netrin-1, we investigated whether defects in these receptors accumulate in a systematic or stochastic manner during the progression of gastric carcinoma." (PMID 26207151, 2015). "In this study, we found that 97 % of gastric cancers with CIN and 55 % of those without CIN showed simultaneous alterations in both DCC and UNC5C, supporting our hypothesis that inactivation of both receptors may be required in the development of gastric cancer." (PMID 26207151, 2015).
hereditary colorectal cancer (2 papers, 2016). "In conclusion, our results suggest that the contribution of germline mutations in UNC5C to hereditary colorectal cancer and to polyposis cases is negligible." (PMID 26852919, 2016).
neuroblastoma (2 papers, 2016 to 2020). Neuroblastoma (NB) is the most common solid, extracranial childhood tumor. "While Pea3 upregulates transcription of Sema3D and represses Sema5B, for example, Erm and Er81 upregulate Sema5A and Er81 regulates Unc5C and Sema4G while repressing EFNB3 in SH-SY5Y neuroblastoma cells." (PMID 33097800, 2020). "Protein expression in these cells showed sensitivity to subtilisin and chymotrypsin similar to that of the adult brain tissue and neuroblastoma cells, with subtilisin at 100nM producing a substantial reduction in neogenin expression but no change of unc-5C or RhoA expression." (PMID 27716118, 2016).
polyposis (2 papers, 2016). "To achieve this goal we sequenced the coding region and exon-intron boundaries of UNC5C in 544 familial CRC or polyposis patients (529 families), using a technique that combines pooled DNA amplification and massively parallel sequencing." (PMID 26852919, 2016). "Here we aim at providing a more conclusive answer about the contribution of germline UNC5C mutations to genetically unexplained hereditary CRC and/or polyposis cases." (PMID 26852919, 2016).
amyloid (1 paper, 2025). "Next, we determined whether amyloid pathology exacerbated UNC5C T835M-mediated effects on plaque-associated neuritic dystrophy, another indicator of neuronal dysfunction." (PMID 40468412, 2025). "We further wanted to understand how the molecular underpinnings of the UNC5C-mediated cell death pathway were affected in the presence of amyloid at 6- and 12-months." (PMID 40468412, 2025). "Indeed, we observed in the hippocampi of dKI mice a significant increase in NOX1 and phosphorylated JNK/SAPK/total JNK at 6 months, while CDK5 was significantly increased by 12 months, suggesting that the UNC5C T835M-mediated apoptotic pathway was exacerbated by amyloid pathology in dKI mice." (PMID 40468412, 2025).